RB1 (RB transcriptional corepressor 1)
Diseases named in the same sentence as RB1 in open-access papers (continued):
Sharing a sentence is not in itself a finding about the gene and the disease.
retinoblastoma (continued). "For example, among the most intensively studied TSGs is the RB1 gene that is associated with inherited childhood retinoblastoma." (PMID 32064050, 2020). "One example is retinoblastoma, an exclusively pediatric tumor of the developing retina largely driven by mutations or deletions in the RB1 gene." (PMID 32952610, 2020). "Retinoblastoma (RB) is an inherited retinal disorder (IRD) caused by the mutation in the RB1 gene or, rarely, by alterations in the MYCN gene." (PMID 31835688, 2019). "Specifically, individuals with germ-line Rb1 mutations are at risk of developing trilateral retinoblastoma, a pediatric intracranial neuroblastic tumor." (PMID 31024258, 2019). "Retinoblastoma is a rare pediatric tumor of the retina, caused by the homozygous loss of the Retinoblastoma 1 (RB1) tumor suppressor gene." (PMID 31058073, 2019). "RB1 plays a key role in inhibiting cell cycle progression, and germline mutations of this gene can lead to familial retinoblastoma formation." (PMID 31616462, 2019). "Due to the presence of multiple tumors, patients with bilateral or multifocal retinoblastoma can be presumed to have a germline or mosaic pathogenic RB1 mutation." (PMID 31835688, 2019). "Genetic testing for RB1 pathogenic variants in the blood of retinoblastoma patients is now a standard component of the retinoblastoma evaluation." (PMID 31683923, 2019). "There is still much to learn about the complex genetic and molecular etiologies that underlie retinoblastoma development, and the role RB1 plays in the formation of other malignant tumors." (PMID 31683923, 2019). "By analysing cell-free DNA present in the AH fluid of eyes affected with retinoblastoma, we have developed a screening test capable of detecting somatic RB1 mutations that is comparable to current tests on enucleated tumour tissue." (PMID 30745306, 2019). "When both alleles of the RB1 gene are lost—as in the setting of retinoblastoma—the function of pRB is curtailed, resulting in abnormal cell proliferation and tumor formation." (PMID 31683923, 2019). "The previous observations that epigenetic mechanisms drive cell transformation and tumorigenesis in human and mouse retinoblastoma suggested that epigenome changes also underlie oncogenesis in the zebrafish rb1 tumor model." (PMID 29914980, 2018). "A previous study performed in retinoblastoma, a childhood cancer caused by bi-allelic loss of RB1, indicated that retinal tumorigenesis was driven by E2F1- and E2F3-transcribed genes following the lack of transcriptional repression due to RB loss." (PMID 30220967, 2018). "Retinoblastoma is of particular interest and concern, mainlybecause of the large proportion (40–45%) of cases that have a well-understoodgenetic origin, and the fact that RB1 gene mutations are associated with othercancers in addition to retinoblastoma." (PMID 30131553, 2018). "Biallelic inactivation of RB1 gene is a disease causing mutation of retinoblastoma, the most common intraocular tumor of childhood with an incidence rate of 1 in 14,000–18,000 live births." (PMID 30109230, 2018). "Recently, RB1, a gene that is commonly mutated in retinoblastoma, has been reported to affect the repair efficiencies of HR and NHEJ." (PMID 30109230, 2018). "Previous studies have documented that RB1 is mutated in most retinoblastomas, osteosarcomas, and small-cell lung cancers, but also in other cancer types at lower frequencies." (PMID 29306194, 2018). "Targeted studies on retinoblastoma mouse models showed that Rb1 loss and additional oncogenic stress including PTEN loss led to the activation of Akt and the subsequent inactivation of FOXO1, leading to tumour proliferation." (PMID 29914080, 2018). "RB1-deficient Retinoblastoma tumors are found in both heritable and sporadic forms and occurs at the incidence of 1 in 15,000–20,000 births." (PMID 29868118, 2018).
retinoblastoma (continued). "Retinoblastoma originates in a photoreceptor cell of the retina and is associated with a mutation in the RB1 gene (which is normally responsible for tumour suppression)." (PMID 29915458, 2018). "In many cases of germline retinoblastoma, a mutated RB1 allele is inherited from a parent and is present in all the cells of a child's body." (PMID 29915458, 2018). "For example, familial mutations in BRCA1 gene increase the risk for breast and ovarian cancers, and familial mutations in RB1 gene lead primarily to retinoblastoma." (PMID 29723191, 2018). "The RB1 gene was originally cloned as the genetic cause of the pediatric tumor of the retina, Retinoblastoma." (PMID 29868118, 2018). "Retinoblastoma is rare tumor of the retina caused by the homozygous loss of the Retinoblastoma 1 tumor suppressor gene (RB1)." (PMID 29868118, 2018). "Retinoma/retinocytoma is a rare, benign variant of retinoblastoma that is also caused by mutations in the RB1 gene." (PMID 29124525, 2017). "First, genetic somatic alterations of the RB1 gene can occur and germ line mutations result in retinoblastomas." (PMID 28812991, 2017). "Retinoblastoma (Rb) is a malignant tumor that arises from loss or mutation of both alleles of the RB1 tumor suppressor gene in the developing retina." (PMID 28099942, 2017). "This difference in the number of MYCN‐amplified retinoblastomas carrying two, one, or zero RB1 mutations (eight, four, and six, respectively) compared to MYCN‐low tumors (195, 25, and seven, respectively) was significant (P < 0.001)." (PMID 28211617, 2017). "Childhood retinoblastoma, almost invariably caused by either germline or somatic mutational inactivation of RB1, is also highly responsive to platinum-based chemotherapy." (PMID 28390395, 2017). "Numerous mutations have been described in the RB1 gene but several other genes have also been implicated to play a role in retinoblastoma." (PMID 29124525, 2017). "Retinoblastoma initiation requires the inactivation of both alleles of the RB1 tumor suppressor gene in the developing retina and tumor progression involves additional genomic changes." (PMID 28099942, 2017). "In the familial, hereditary, form of retinoblastoma (~ 40% of all cases) the first mutational hit occurs in the germline, generating an RB1+/− genotype, and the second hit occurs sporadically in the somatic cells." (PMID 29124525, 2017). "It is essential to know the sequence variation that occur in RB1 to understand the molecular mechanisms underlying the various manifestations of retinoblastoma, such as the different degrees of RB penetrance and expressivity." (PMID 29261756, 2017). "Retinoblastoma is a rare intraocular tumor that is caused by a mutation in the retinoblastoma-associated protein (RB1 gene), which acts as a tumor suppressor." (PMID 28420213, 2017). "To define which of the identified mechanisms is present in MYCN‐amplified retinoblastoma, we first investigated MYCN copy number and the mutations present in RB1 in a series of 245 cases of unilateral retinoblastoma." (PMID 28211617, 2017). "As the results suggest that heterogeneity in RB1 mutations affect both the penetrance of retinoblastoma and likely tumor progression it stresses the importance of analyzing parents with hereditary forms of retinoblastoma." (PMID 29124525, 2017). "Retinoblastoma is a pediatric cancer of the retina most often caused by inactivation of the retinoblastoma (RB1) tumor suppressor gene." (PMID 28445155, 2017). "Patients with RB1 mutations that affect E2F binding, with retained ability to induce differentiation of tumor cells, had low penetrance of retinoblastoma." (PMID 29124525, 2017). "One of the mutations shared between the CRPC tissue sample and CTCs was a premature stop codon in the Retinoblastoma (RB1) gene, which is associated with isolated bilateral retinoblastoma and meningioma." (PMID 28228136, 2017).
retinoblastoma (continued). "Germ line mutations in the RB1 gene result in retinoblastomas, a rare form of childhood cancer, and also higher risk of osteosarcomas and other types of cancer." (PMID 28812991, 2017). "Of interest were three cases of mosaic RB1 mutations detected in the blood from patients with unilateral retinoblastoma." (PMID 28575107, 2017). "Spectrum of somatic RB1 point mutations detected only in retinoblastoma tumors in Singaporean cohort." (PMID 28575107, 2017). "Identification of RB1 mutations is essential to assess the risk of developing retinoblastoma in the patients ́ relatives." (PMID 29261756, 2017). "Retinoblastoma, an embryonic neoplasm of retinal origin, was initially thought to be caused exclusively by the loss of function of the retinoblastoma (RB1) gene, but MYCN-amplification has also been reported to initiate the disease." (PMID 28358317, 2017). "Consistent with this, FANCA expression is up-regulated in basal breast tumors compared with non-basal breast tumors, and has higher expression levels in RB1-mutated retinoblastomas than MYCN-amplified retinoblastomas." (PMID 28239445, 2017). "In rare cases, pediatric patients with hereditary retinoblastoma harboring rb1 mutation are at an increased risk for pineoblastoma, supratentorial PNET, and medulloblastoma." (PMID 28903419, 2017). "Assuming a sensitivity for finding a coding sequence RB1 mutation to be 94% 4, one would expect to observe only one wild‐type RB1+/+ retinoblastoma among the 245 tested." (PMID 28211617, 2017). "Fifteen percent of unilateral retinoblastoma occur due to de novo germline RB1 mutations which is transmissible in subsequent generations." (PMID 28575107, 2017). "The role of RB1 mutations in retinoblastoma development is well understood, however, little is known about the etiology of these mutations and the possible role of environmental exposures." (PMID 26991078, 2016). "While RB1 loss initiates retinoblastoma development, additional somatic copy number alterations (SCNAs) can drive tumor progression." (PMID 27115612, 2016). "Retinoblastoma is a malignant tumor of the retina in children <5 years of age and occurs after two mutations in the RB1 gene." (PMID 26753011, 2016). "The RB1 gene is tumor suppressor gene identified and loss of it is considered an accelerating event in retinoblastoma." (PMID 28155630, 2016). "Our results show that retinoblastoma is among the least mutated cancers and signify the extreme sensitivity of the childhood retina for RB1 loss." (PMID 27126562, 2016). "Since the discovery of RB1 mutations, much effort has been invested into finding the cell-of-origin for retinoblastoma and understanding the carcinogenic mechanisms in those cells." (PMID 27486389, 2016). "By definition, RB1 germ line mutations detected by DNA diagnostics were associated with familial and heritable retinoblastoma." (PMID 27126562, 2016). "RB1 mutations occur in almost all familial and sporadic forms of retinoblastoma, and this gene is mutated at variable frequencies in a variety of other human cancers." (PMID 27401552, 2016). "Familial hereditary Rb is defined as two or more carriers of an RB1 germline gene mutation in a family and represents 10% of all retinoblastomas." (PMID 26925970, 2016). "Significantly, individual types of cancer typically associate with particular lesions in this network (e.g., mutation of RB1 in retinoblastoma, mutation of INK4A in pancreatic cancer, amplification of Cyclin D1 in breast tumors, etc.)." (PMID 27401552, 2016). "Retinoblastoma can thus develop either in a heritable manner, due to a germline RB1 mutation followed by a somatic RB1 inactivation, or in a sporadic manner due to two independent somatic RB1 mutations." (PMID 27739525, 2016). "Silencing by methylation of the RB1 promoter has been observed in retinoblastoma tumors as a second mutation (M2) and is classified as somatic epimutation." (PMID 26753011, 2016).
retinoblastoma (continued). "Retinoblastoma is an ocular neoplastic cancer caused primarily due to the mutation/deletion of RB1 gene." (PMID 27799869, 2016). "Despite the identification of loss or inactivation of the RB1 gene as the main genetic driver responsible for the development of retinoblastoma, recent studies have suggested that additional pathways and genes are involved." (PMID 27661116, 2016). "Patients with familial or sporadic heritable retinoblastoma have a germ line mono-allelic RB1 mutation and have acquired a second RB1 hit in the retina." (PMID 27126562, 2016). "Cancer genome sequencing confirmed that RB1 is mutated in most retinoblastomas, osteosarcomas, and small-cell lung cancers, and it is mutated at lower frequencies in a variety of other cancer types." (PMID 27401552, 2016). "Using an optimized multi-step mutation scanning protocol for tumor DNA, the spectrum of mutations in RB1 gene was established in 37 unrelated Tunisian patients with sporadic retinoblastoma." (PMID 25602518, 2015). "In the Tunisian population, the proportion of isolated unilateral retinoblastoma patients 20% (7/36) who carry RB1 mutant allele at constitutional level is higher than previous reports." (PMID 25602518, 2015). "In several instances, retinoblastoma disease occurs in one eye only, even when Rb1 is mutated in all cells of the body." (PMID 26176933, 2015). "The mean age of retinoblastoma diagnosis is 9 to 15 months for children with germline RB1 mutations and 23 to 36 months for children with somatic gene mutations." (PMID 26230335, 2015). "The aim for the present study was to identify the spectrum of mutations of RB1 gene in 37 unrelated patients of Tunisian origin with unilateral retinoblastoma and to seek correlations between mutation status and clinical features." (PMID 25602518, 2015). "It has been known that approximately 15% of individuals with sporadic unilateral retinoblastoma, carry a germline mutation in RB1." (PMID 25602518, 2015). "Rb1 is the most frequently mutated gene in the pediatric cancer retinoblastoma, and its loss causes E2F transcription factors to induce proliferation related genes." (PMID 25907958, 2015). "The retinoblastoma susceptibility gene, RB1 (Genbank accession number L11910.1; NCBI RefSeq NM_000321.2) is located on chromosome 13q14.2 and is composed of 27 exons distributed along 183 kb of genomic sequence." (PMID 25928201, 2015). "It was shown recently that retinoblastoma patients with the hereditary type (RB1 deletion) have an increased risk of uLMS; 3,2% of patients developed uLMS, which corresponds to an excess risk of 3,9/10000 women." (PMID 26576131, 2015). "Retinoblastoma, a very aggressive cancer of the developing retina, initiatiates by the biallelic loss of RB1 gene, and progresses very quickly following RB1 inactivation." (PMID 26143641, 2015). "Retinoblastoma is the most common eye cancer in children, which is caused by mutation of the RB1 gene." (PMID 26464030, 2015). "It is known, that mutations in RB1, that result in altered protein structure with partial retention of protein function, are over-represented in unilateral retinoblastoma." (PMID 25602518, 2015). "Surprisingly, deep sequencing of human retinoblastoma tumors has uncovered an extremely low mutation rate, with only the RB1 gene itself emerging as a highly mutated gene in this cancer." (PMID 25907958, 2015). "We analyzed DNA from tumor tissue and from peripheral blood to determine the RB1 mutation status and seek correlations with clinical features of 37 unrelated cases of Tunisian origin with sporadic retinoblastoma." (PMID 25602518, 2015). "Retinoblastoma (RB) is the most common malignant childhood tumor of the eye and results from inactivation of both alleles of the RB1 gene." (PMID 26530098, 2015). "Retinoblastoma is a rare cancer of the retina which presents in early childhood, typically caused by a mutation in the RB1 tumor suppressor gene." (PMID 26230335, 2015).
retinoblastoma (continued). "Results of a previous study found that the incidence of retinoblastoma occurs in only 36% of patients with certain Rb1 mutations." (PMID 26176933, 2015). "For instance, mutational inactivation of both Rb1 alleles is the primary molecular cause of retinoblastoma." (PMID 24757565, 2014). "Most retinoblastomas initiate with biallelic inactivation of the RB1 gene through diverse mechanisms including point mutations, nucleotide insertions, deletions, loss of heterozygosity and promoter hypermethylation." (PMID 24509483, 2014). "In RB1-mutated retinoblastoma, all three activating E2Fs were significantly upregulated: E2F1 (FC = 1.86, P = 2.56E-03), E2F2 (FC = 2.84, P = 2.31E-04), and E2F3 (FC = 3.72, P = 2.18E-10)." (PMID 25161863, 2014). "Retinoblastoma, the most common intraocular malignant tumor in children, is characterized by the loss of both functional alleles of RB1 gene, which however alone cannot maintain malignant characteristics of retinoblastoma cells." (PMID 25359779, 2014). "Gallie and colleagues discovered that a small proportion of retinoblastomas lack RB1 mutations and had MYCN amplification." (PMID 24509483, 2014). "Although the loss of functional Rb1 gene is one of the hallmarks of retinoblastoma, its major effect is the initiation of stable retinoma, a benign tumor, with low level genomic instability." (PMID 25359779, 2014). "This trend mirrors the main initiating factor in the pathogenesis of retinoblastoma: loss of functional alleles of RB1 gene and resultant inactive retinoblastoma protein, which is involved in the control of cell cycle." (PMID 25359779, 2014). "Expression of 14 FA genes was monitored in two human cell-cycle models and in two RB1/E2F pathway-associated primary cancers, retinoblastoma and basal breast cancer." (PMID 25161863, 2014). "Approximately 10% of retinoblastomas are inherited and are caused by germ-line transmission of one mutated Rb1 allele and loss of the remaining wild-type allele in somatic retinal cells." (PMID 24757565, 2014). "The vast majority of retinoblastomas harbors mutations in RB1, while it has been recently recognized that functional loss of RB1 is a common event in basal like breast tumors." (PMID 25161863, 2014). "Most retinoblastomas are believed to initiate with biallelic inactivation of the retinoblastoma susceptibility gene (RB1) which is rate limiting for tumorigenesis." (PMID 24509483, 2014). "Retinoblastoma is a genetically determined tumor due to mutations or deletions of both copies of RB1, a tumor-suppressor gene encoding a 110 kDa nuclear protein involved in the control of neoplastic growth." (PMID 24498108, 2014). "We also analyzed the RB1 gene mutations and compared the mechanism of RB1 inactivation to the recurrent copy number variations in the retinoblastoma genome." (PMID 24509483, 2014). "Most cases of retinoblastoma are characterized by the loss of both functional alleles of RB1 gene in tumors." (PMID 25359779, 2014). "These retinal cancer cells, caused by the loss of function of two gene alleles (Rb1) that encode the retinoblastoma tumour suppressor, have elevated expression of ILK." (PMID 24911651, 2014). "Retinoblastoma is a rare childhood cancer of the developing retina that initiates with biallelic loss of the RB1 gene." (PMID 23765217, 2013). "Despite these advantages, there are many challenges in molecular genetic diagnosis of retinoblastoma because of the large size of the RB1 gene and widely dispersed mutations." (PMID 23441118, 2013). "Despite the growing number of studies that have used MLPA to analyze genes in various human diseases, only a few have used it in evaluating RB1 mutations in retinoblastoma and other cancers." (PMID 23441118, 2013). "Retinoblastoma is a childhood ocular tumor that develops from loss of functional retinoblastoma protein (pRb) as a result of genetic or epigenetic changes that affect both alleles of the RB1 gene." (PMID 23826078, 2013).